INS (insulin)
Diseases named in the same sentence as INS in open-access papers (continued):
Sharing a sentence is not in itself a finding about the gene and the disease.
Insulin resistance (continued). "Significantly increased fasting plasma glucose, fasting serum insulin and insulin resistance (in terms of the homeostatic model assessment for insulin resistance, HOMA-IR) were demonstrated in HFHC-fed mice compared with that of the CON group (p < 0.01)." (PMID 36308318, 2022). "Such improvement of glycemic control reduces glucose toxicity and thus mitigates insulin resistance by improving insulin signaling in insulin target organs." (PMID 35918386, 2022). "The glucose infusion rate (GIR) was lower in the HFD-CHOW group, indicative of insulin resistance, and C-peptide levels trended lower, consistent with defective insulin secretion." (PMID 36107617, 2022). "CNI can induce decreased insulin secretion, increased insulin resistance, and direct toxicity on β cells." (PMID 36013220, 2022). "They found reductions in mtDNA copy number and increased mtDNA D-loop methylation correlated with insulin resistance, which they propose was an insulin signaling-epigenetic-genetic axis in mitochondrial regulation." (PMID 36093112, 2022). "Patients with NAFLD almost universally exhibit systemic insulin and hepatic insulin resistance in addition to adipose tissue and muscle insulin resistance, which are all contributing to the clinical phenotype in diabetes mellitus." (PMID 36101976, 2022). "C. paliurus flavonoids have been demonstrated to reduce food intake, body weight, serum insulin level, and insulin resistance in SHR/CP rats." (PMID 35956345, 2022). "What are the downstream effects of CNS insulin resistance and what are the mechanisms by which CNS insulin influences cognition?" (PMID 35884888, 2022). "We investigated the effect of SGLT2i treatment on insulin resistance, insulin secretion, incretin levels, body composition, and hepatic insulin clearance." (PMID 35115614, 2022). "Adipose tissue macrophages (ATMs) infiltrate adipose tissue in obesity, and M1-activated cells secrete an array of proinflammatory cytokines that drive insulin resistance, while M2-cells promote insulin sensitivity through Il-10 signaling." (PMID 35957819, 2022). "Insulin resistance (IR) is a general term meaning that adipose tissue, skeletal muscle, liver and pancreas display a low response to insulin action." (PMID 35906587, 2022). "We believe the adipose tissue insulin resistance is a stronger predictor of ketonemia than fat mass percentage, as insulin sensitivity limits adipose tissue lipolysis, which decreases the amount of NEFA available for ketogenesis." (PMID 35874514, 2022). "HF feeding increases the levels of fasting glucose and insulin in circulation, leading to glucose intolerance and insulin resistance." (PMID 35628137, 2022). "At the end of the study, the results showed significant improvements in plasma insulin and insulin resistance in this group compared to the placebo arm43." (PMID 35982162, 2022). "Tau knock-out mice have impaired IRS-1 tyrosine phosphorylation (required to activate insulin signaling) and increased Ser636 IRS-1 phosphorylation (which inhibits insulin signaling) leading to insulin resistance." (PMID 35281504, 2022). "Increased GH concentrations during early postpartum (PP) act as an antagonistic to insulin by enhancing lipolysis and developing insulin resistance (IR) to help direct nutrients from insulin-sensitive tissues to the lactating mammary gland." (PMID 36153497, 2022). "Our study confirmed that serum insulin levels and insulin resistance assessed by HOMA-IR in the first trimester were significantly increased in women who later developed GDM compared with those who did not develop GDM." (PMID 36465627, 2022). "While previous studies had utilized morpholino-knockdown or transgenesis to induce insulin resistance, we used insulin solution by immersing 20–30 zebrafish larvae per group." (PMID 35955446, 2022).
Insulin resistance (continued). "Hepatic insulin resistance state and impairment in insulin signaling were additionally confirmed in our MS model by a remarkable reduction in the hepatic expression of IRS-2." (PMID 35990819, 2022). "Five patients of the overall cohort showed insulin-resistance defined as glucose/insulin ratio < 6 and/or Homeostasis model assessment of insulin resistance (HOMA-IR index) > 2.5." (PMID 35854365, 2022). "Chronic ethanol feeding induces insulin resistance that markedly impairs the anti-lipolytic effects of insulin in WAT, enhancing TG breakdown to release free FA into the circulation." (PMID 35864895, 2022). "Comparisons of total GLP-1 levels, insulin resistance, and insulin sensitivity indices in NGT, pre-DM, and T2DM." (PMID 36157456, 2022). "Decreased insulin secretion increased postload glucose concentration, and elevated insulin resistance increases FPG." (PMID 36432554, 2022). "The glucose that is not converted to glycogen in the muscles is directed to the liver, leading to a compensatory increase in insulin levels and the onset of progressive insulin resistance." (PMID 35920204, 2022). "Although macronutrient patterns are predictive of insulin resistance, research also shows that some micronutrients, particularly vitamin D, are related to insulin sensitivity, as well as type 2 diabetes." (PMID 35565811, 2022). "Insulin resistance identifies any condition in which the response of metabolic target tissues, namely, skeletal muscle, fat, and liver, to normal circulating levels of insulin is impaired." (PMID 36289636, 2022). "The restoration of the insulin signaling pathway can alleviate the symptoms of insulin resistance, restore the utilization of insulin by cells, and increase insulin activity." (PMID 36558381, 2022). "It has broadly been attributed to defects in insulin secretion and increasing insulin resistance, the latter often arising because of obesity and physical inactivity." (PMID 35948367, 2022). "Determining, in turn, a modification of insulin signaling pathways, thus worsening the systemic state of insulin resistance." (PMID 35054072, 2022). "Previous animal experiments have shown that the acupoints CV4 and SP6 can activate SIRT1/PGC-1α in skeletal muscle and regulate the expression of key insulin signaling-related molecules, thus relieving insulin resistance in obese diabetic mice." (PMID 35903320, 2022). "Insulin resistance implies that insulin levels are lower than expected by the body, therefore leading to various effects on different tissues depending on the metabolic demands." (PMID 35454166, 2022). "Both the average fasting insulin and insulin resistance index of the NAFLD patients in the obesity group were significantly higher than those in the lean group (B1 vs. B2, p < 0.05)." (PMID 35860380, 2022). "First, to model insulin resistance in these cells, Akt (PKBα) activation with increasing insulin concentrations applied shortly before harvest was established." (PMID 35061720, 2022). "HOMA2-IR is primarily an index of hepatic insulin resistance but also shows a good correlation with the hyperinsulinaemic–euglycaemic clamp, the ‘gold-standard’ technique for evaluating insulin-stimulated glucose metabolism and whole-body insulin resistance." (PMID 34800144, 2022). "Alendronate also play important role in improving fasting plasma glucose and insulin sensitivity and decreases insulin resistance in prediabetic osteopenic postmenopausal women." (PMID 35027504, 2022). "Metformin was mostly studied in context of reversing the effects of insulin resistance on the insulin signaling pathway." (PMID 35873556, 2022). "It occurs when beta cells fail to provide sufficient insulin amounts or in cases of increased insulin resistance (IR)." (PMID 36428943, 2022).
Insulin resistance (continued). "TMAO has been shown to induce DM2 via increasing fasting insulin levels and insulin resistance (HOMA-IR) in animal models, whereas studies in humans have shown that high TMAO levels are associated with an increased risk of DM2." (PMID 36428943, 2022). "For example, mutants of InR, chico, Dp110, Akt1, Rheb, and S6K disrupt the Insulin/TOR pathway and cause varying degrees of insulin resistance respectively." (PMID 36035393, 2022). "So far, the only effective treatment method has been direct insulin injection for insulin-resistant (IR) patients." (PMID 35055294, 2022). "Given the close link between impaired insulin actions and HF, the correction of insulin resistance and hyperinsulinemia induced by SGLT2 inhibition likely contributed to the clinical benefits observed in those CVOTs." (PMID 35941584, 2022). "Insulin and insulin resistance suppresses SHBG production, resulting in increased circulating free testosterone levels and enhanced hyperandrogenism." (PMID 36457554, 2022). "It indicated that the insulin signaling transduction pathway was involved in the insulin resistance of KK-Ay mice." (PMID 35153796, 2022). "Both TNF-α and IL-6 can lead to insulin resistance by triggering different key steps in the insulin signalling pathway." (PMID 36501129, 2022). "Prediabetes is characterized by peripheral insulin resistance, such that the peripheral tissues like skeletal muscle and adipose tissue fail to appropriately respond to the insulin released from the pancreas." (PMID 35222279, 2022). "Type 2 diabetes is characterized by hyperglycemia, insulin resistance and inadequate secretion of insulin, each of which plays a role in the pathogenesis of EC." (PMID 35615721, 2022). "As an adipokine, FABP4 has been reported to stimulate hepatic glucose production and augment insulin secretion, contributing to insulin resistance and hyperglycemia." (PMID 35909571, 2022). "Insulin resistance, i.e. reduced cell sensitivity to insulin and compensatory hyperinsulinemia, induce an early response to luteinizing hormones and cause premature differentiation of small follicles, resulting in anovulation." (PMID 36733805, 2022). "This translated into retained insulin sensitivity as measured by a significantly lower average homeostatic model assessment for insulin resistance (HOMA‐IR) score in Il1r1Hep−/– mice." (PMID 36101976, 2022). "Chronic inflammatory responses and immune disorders in insulin-sensitive tissues and pancreatic islets contribute to insulin resistance, islet β-cell destruction, and the onset of T2DM." (PMID 35505375, 2022). "Because of the wide range of insulin actions in the body, it is anticipated that assessing insulin resistance can be challenging." (PMID 35651975, 2022). "The chronic elevation of FFA fuels insulin resistance and exerts detrimental effects on insulin secretion, gene expression, and β-cell survival as well, mostly due to increased oxidative and endoplasmic reticulum stress, GLUT translocation, and inflammation." (PMID 35453472, 2022). "PUG-1 can also promote glucose utilization in peripheral tissues, improve insulin sensitivity and increase the number of insulin receptors, and improve insulin resistance." (PMID 36176638, 2022). "Leptin has a potent effect on insulin signalling and treatment of ob/ob and other lipodystrophic mice with physiological leptin doses rescues insulin resistance." (PMID 35844058, 2022). "Another study in mice found that dendritic cells drive mechanisms to increase the insulin reserve in response to obesity-induced insulin resistance." (PMID 35634436, 2022). "ER stress is considered an important event in insulin resistance; therefore, we investigated the ability of tunicamycin, a known ER stress inducer, to regulate insulin signaling in Huh-7 cells." (PMID 36079898, 2022).
Insulin resistance (continued). "Mechanistically, insulin resistance and the resultant hyperinsulinemia promotes endometrial carcinogenesis and progression by the direct pro-proliferative and anti-apoptotic effect of insulin and insulin growth factor (IGF-1) on endometrial cells." (PMID 35600348, 2022). "Insulin resistance can be evaluated indirectly via validated indices, calculated using insulin and glucose blood levels." (PMID 35921366, 2022). "Overexpression of AhR leads to insulin resistance, while AhR-null mice have enhanced insulin sensitivity and improved glucose tolerance." (PMID 36499198, 2022). "In situations of insulin resistance, beta cells increase the production of insulin to compensate for the higher peripheral insulin demand, thereby enhancing ER function." (PMID 35629947, 2022). "Insulin resistance is characterized by the reduced ability of insulin to regulate glucose homeostasis, which leads to hyperinsulinemia and metabolic disruptions." (PMID 36570152, 2022). "Recent studies have demonstrated that upregulating autophagy genes lead to amelioration of insulin resistance and enhancement of insulin sensitivity in obese mice." (PMID 35017319, 2022). "In insulin resistance, body tissues are unable to sense insulin and insulin becomes unable to take glucose inside the cells for glucose homeostasis in the body." (PMID 36079819, 2022). "The inability of responding to insulin in insulin-sensitive metabolic tissues, known as insulin resistance, is one of the main pathophysiology of T2DM, thus the tissues cannot uptake glucose from the blood easily." (PMID 36232291, 2022). "On the other hand, the pathophysiology of T2DM is more complicated and involves impaired insulin secretion from pancreatic β-cells as well as peripheral insulin resistance." (PMID 35901054, 2022). "Many studies support a relationship between pathological conditions characterized by insulin dysfunction, such as impaired glucose tolerance, insulin resistance, and DM, and AD." (PMID 35615716, 2022). "Insulin resistance is characterized by the maintenance of high plasma insulin concentrations but with a decrease in the ability of cells to respond to insulin action." (PMID 36648872, 2022). "Insulin resistance and alterations in relative insulin secretion have been implied as the main pathophysiological causes of T2D." (PMID 35770520, 2022). "In patients with Alzheimer’s disease, metabolic imbalance, such as central and peripheral insulin resistance and impaired insulin signaling, were observed." (PMID 35328405, 2022). "Insulin resistance is defined as the impairment of the insulin-mediated glucose disposal by the body." (PMID 35887101, 2022). "T2DM is characterized by insulin resistance, followed by insulin hypersecretion in β-cells of Langerhans." (PMID 35807304, 2022). "In patients with insulin resistance, the inhibitory effects of insulin on platelets are impaired, due to the abnormal adipokine content." (PMID 35250588, 2022). "Due to the pleiotropic effects of insulin, insulin resistance co-occurs with other cardiometabolic abnormalities, such as visceral adiposity, hypertension, dyslipidemia, hyperuricemia, and low-grade inflammation." (PMID 36432614, 2022). "The authors concluded that the activation of FXR via CDCA resulted in a reversal of the insulin resistance, resulting in normalized plasma insulin levels and insulin sensitivity." (PMID 35214975, 2022). "An increase in free fatty acid levels can be brought about by a worsening of insulin sensitivity; inducing tissue oxidative stress will contribute to the development of insulin resistance in tissues." (PMID 35251371, 2022). "Recently described non-insulin-based IR index, the metabolic score for insulin resistance (METS-IR), was developed with the aim to quantify peripheral insulin sensitivity." (PMID 36012003, 2022). "In normal situation, insulin has an inhibitory effect on hormone-sensitive lipase in the adipose tissue (AT) leading to insulin resistance (IR)." (PMID 35484544, 2022).
Insulin resistance (continued). "The hyperinsulinemic-euglycemic clamp and the insulin suppression test are both direct assessment methods for insulin resistance." (PMID 36452320, 2022). "Key factors in the pathogenesis of type 2 diabetes are a combination of insulin resistance, insufficient insulin secretory capacity, and genetic disposition combined with excess energy intake and physical inactivity." (PMID 36531168, 2022). "The three training interventions led to significant decreases in Homa-IR and insulin levels (p < 0.01), with the greater improvement of insulin resistance in G50 compared to G75 and G50/75 (p < 0.05)." (PMID 36554057, 2022). "We aimed to investigate the role of Sam68 in insulin signaling and the possible implications of Sam68 in the insulin resistance in PCOS." (PMID 36139396, 2022). "Poor insulin sensitivity or insulin resistance is a predictor of T2DM and is observed in hypertension, dyslipidemia and cardiovascular diseases." (PMID 35205333, 2022). "Hepatic insulin resistance, defined as impaired suppression of glucose production by insulin in hepatocytes, is also an important component in metabolic disorders." (PMID 36496443, 2022). "Here, we show that oral administration of Rb1 significantly decreased serum LDL-c, TG, insulin, and insulin resistance index (HOMA-IR) in mice with a high-fat diet (HFD)." (PMID 35516426, 2022). "We additionally found that patients with obesity had greater insulin resistance and lower insulin sensitivity based on HOMA-IR and WBISI indices respectively, and these differences were clinically significant." (PMID 35842601, 2022). "This suggests that fat body impairment in insulin signaling triggers insulin resistance (IR) and diabetic phenotypes." (PMID 35734406, 2022). "Another relevant set of data we documented in the present study is related to insulin signaling defects in Alb-R26Met livers, which strikingly correlated with hepatocyte-specific insulin resistance." (PMID 35269415, 2022). "Vitamin D3 plays a role in the prevention of insulin resistance by improving insulin secretion, glucose metabolism, glucose tolerance, insulin sensitivity and inhibiting systemic inflammation." (PMID 36352900, 2022). "Insulin resistance, characterized by high insulin secretion by beta cells to compensate for high blood glucose, is an underlying key condition of MetS." (PMID 35802721, 2022). "When insulin resistance occurs, the amount of insulin needed to maintain normal blood glucose will increases." (PMID 36359836, 2022). "DPP4 also interferes with insulin signaling, reducing Akt phosphorylation, thus contributing to the development of insulin resistance; for all these reasons, the detection of elevated sDPP4 levels in the presence of obesity is somehow expected." (PMID 36140405, 2022). "The basal glucose, CPbaseline, basal human insulin, homeostatic model assessment of insulin resistance, IAsp dose, and demographic statistics were all comparable between the 2 groups except the “clamped” glucose." (PMID 35384402, 2022). "T2DM is mainly characterized by hyperglycemia, which eventually results in chronic insulin resistance in insulin-sensitive tissues and defective insulin secretion by pancreatic β-cells." (PMID 36232291, 2022). "Some of the proposed theories reveal that chronic inflammation, insulin resistance, hyperinsulinemia, hyperglycemia, and abnormalities in the insulin and insulin-like growth factor axis (IGF) contribute to the disease association between these two conditions." (PMID 35898377, 2022). "Metformin reduces insulin resistance by increasing insulin sensitivity in the liver and peripheral tissues." (PMID 35368950, 2022). "Insulin resistance is a common pathophysiological status in which individuals have decreased insulin sensitivity and impaired glucose regulation by insulin, resulting in glucose intolerance." (PMID 36432623, 2022).